TGFB2 (transforming growth factor beta 2)
Description:
[Transforming growth factor beta-2 proprotein]: Precursor of the Latency-associated peptide (LAP) and Transforming growth factor beta-2 (TGF-beta-2) chains, which constitute the regulatory and active subunit of TGF-beta-2, respectively. [Latency-associated peptide]: Required to maintain the Transforming growth factor beta-2 (TGF-beta-2) chain in a latent state during storage in extracellular matrix (By similarity). Associates non-covalently with TGF-beta-2 and regulates its activation via interaction with 'milieu molecules', such as LTBP1 and LRRC32/GARP, that control activation of TGF-beta-2 (By similarity). [Transforming growth factor beta-2]: Multifunctional protein that regulates various processes such as angiogenesis and heart development. Activation into mature form follows different steps: following cleavage of the proprotein in the Golgi apparatus, Latency-associated peptide (LAP) and Transforming growth factor beta-2 (TGF-beta-2) chains remain non-covalently linked rendering TGF-beta-2 inactive during storage in extracellular matrix (By similarity). At the same time, LAP chain interacts with 'milieu molecules', such as LTBP1 and LRRC32/GARP, that control activation of TGF-beta-2 and maintain it in a latent state during storage in extracellular milieus (By similarity). Once activated following release of LAP, TGF-beta-2 acts by binding to TGF-beta receptors (TGFBR1 and TGFBR2), which transduce signal (By similarity).
Synonyms: G-TSF; CAEND2; LDS4; TGF-beta2
Tractability: Antibody: a drug acting on it is in phase 2 or 3 trials; its Gene Ontology location is reachable by antibodies, with high confidence; UniProt places it where antibodies can reach, with medium confidence; UniProt predicts a signal peptide or a membrane-spanning region. PROTAC: ubiquitination databases record sites on it; a small molecule that binds it is known. Other modalities: an approved drug acts on it.
Target class: Secreted protein
Gene: Protein-coding gene on chromosome 1 (218,345,336 to 218,444,619, forward strand). Ensembl gene ENSG00000092969.
Subcellular location: Secreted, extracellular space, extracellular matrix (Latency-associated peptide); Secreted (Transforming growth factor beta-2)
Subcellular location (Human Protein Atlas): Vesicles; Predicted to be secreted
Pathways (Reactome):
Extracellular matrix organization: ECM proteoglycans; Molecules associated with elastic fibres
Signal Transduction: TGF-beta receptor signaling activates SMADs; TGFBR3 regulates TGF-beta signaling
Hemostasis: Platelet degranulation
Gene Ontology:
Molecular function: amyloid-beta binding; protein binding; protein homodimerization activity; signaling receptor binding; transforming growth factor beta receptor binding; type II transforming growth factor beta receptor binding; type III transforming growth factor beta receptor binding; cytokine activity; growth factor activity
Biological process: cardiac epithelial to mesenchymal transition; cardiac muscle cell proliferation; cardioblast differentiation; cell migration; cell morphogenesis; cell-cell junction organization; collagen fibril organization; embryonic digestive tract development; epithelial cell differentiation; epithelial to mesenchymal transition; extrinsic apoptotic signaling pathway; eye development; glial cell migration; hair follicle development; heart development; heart morphogenesis; negative regulation of angiogenesis; negative regulation of cell growth; negative regulation of cell population proliferation; negative regulation of epithelial cell proliferation; negative regulation of gene expression; negative regulation of macrophage cytokine production; positive regulation of cardioblast differentiation; positive regulation of cell adhesion mediated by integrin; positive regulation of cell growth; and 81 more
Cellular component: extracellular matrix; extracellular region; axon; neuronal cell body; platelet alpha granule lumen; transforming growth factor beta complex; endosome
Genetic constraint (gnomAD): Loss-of-function variants: 12 observed, 42.01 expected, observed/expected ratio (o/e) 0.29, 90% interval 0.18 to 0.46. The upper end of that interval is the gene's LOEUF score, 0.46, which puts it in group 2 of 6, group 1 being the genes least tolerant of losing a copy. Missense variants: 389 observed, 539.23 expected, observed/expected ratio (o/e) 0.72, 90% interval 0.66 to 0.79. Synonymous variants: 193 observed, 204.84 expected, observed/expected ratio (o/e) 0.94, 90% interval 0.84 to 1.06.
Gene-disease validity (ClinGen):
ClinGen rates the evidence that TGFB2 causes each of these diseases.
familial thoracic aortic aneurysm and aortic dissection (autosomal dominant): Definitive. A rare genetic vascular disease characterized by the familial occurrence of thoracic aortic aneurysm, dissection or dilatation affecting one or more aortic segments (aortic root, ascending aorta, arch or descending aorta) in the absence of any other associated disease.
Homologues: Orthologues: chimpanzee TGFB2 (99% identical), macaque TGFB2 (99% identical), dog TGFB2 (99% identical), pig TGFB2 (99% identical), rabbit TGFB2 (99% identical), mouse Tgfb2 (96% identical), rat Tgfb2 (95% identical), guinea pig TGFB2 (95% identical), tropical clawed frog tgfb2 (86% identical), zebrafish tgfb2 (79% identical). Paralogues in human: TGFB3 (55% identical), TGFB1 (43% identical), MSTN (23% identical), GDF11 (22% identical), BMP6 (22% identical), BMP7 (22% identical), BMP2 (22% identical), BMP4 (22% identical), BMP5 (20% identical), GDF6 (20% identical), BMP10 (20% identical), GDF5 (20% identical), and 19 more.
Diseases named in the same sentence as TGFB2 in open-access papers:
TGFB2 is named in the same sentence as 391 diseases in open-access papers, as found by Europe PMC text mining. Sharing a sentence is not in itself a finding about the gene and the disease. The quoted sentences say what the papers report.
glaucoma (140 papers, 2008 to 2026). Increased pressure in the eyeball due to obstruction of the outflow of aqueous humor. "Previous research has established that TGFβ2, another isotype, is found in high concentrations within the aqueous humor of patients with primary open-angle glaucoma and is implicated in instability in the blood–aqueous barrier." (PMID 38391628, 2024). "Recent studies on epigenetics and glaucoma suggested that histone acetylation has an important role in increased expression of the glaucoma-associated factor TGFβ2 resulting in damage to TM." (PMID 38474069, 2024). "Of particular interest is the upregulated expression and secretion of TGFβ2 in autophagy-deficient cells, as TGFβ2 is present at higher concentrations in the AH from glaucoma patients." (PMID 37034386, 2023). "Although elevated TGFβ2 levels appear to be a causative factor in glaucoma pathogenesis, little is known about how TGFβ2 expression is regulated in the trabecular meshwork (TM)." (PMID 36766846, 2023). "Together, these findings identify miR-18a-5p as a mediator of the TGFβ2 response and a candidate therapeutic agent for glaucoma via its ability to inhibit CTGF-associated increased TM contractility." (PMID 36011411, 2022). "Of the several glaucoma-associated molecular markers identified, TGFβ2 has an imperative role in POAG progression." (PMID 35805889, 2022). "TGFβ2 levels (pro and active) are elevated both in steroid-induced glaucoma and myocilin-associated glaucoma, suggesting that TGFβ2 signaling is an important mediator in OHT models." (PMID 34830390, 2021). "Although there is conflict in reports, it is clear that high TGFβ2 or relatively high TGFβ2 (assuming TGFβ2 decreases with age) is associated with glaucoma." (PMID 34499703, 2021). "Pathology associated with disease conditions such as protein misfolding (myocilin-associated glaucoma) or increased synthesis (steroid or TGFβ2-induced glaucoma) can disturb protein homeostasis in the ER, resulting in ER stress." (PMID 34830390, 2021). "Treatment with TGFB2, a glaucoma associated growth factor, resulted in an increased ECM deposition in the TM of corneoscleral segments." (PMID 32579557, 2020). "Transforming growth factor β2 (TGFβ2) is elevated in the AH and TM of primary open angle glaucoma (POAG) patients and induces POAG-associated TM changes, including CLANs." (PMID 28241317, 2017). "Of particular interest to this work, TGFβ2 has been linked to most types of glaucomas as a potential fibrotic agent that can cause elevation of intraocular pressure (IOP)." (PMID 27924833, 2016). "If that is true, it is very likely that the other glaucoma-associated factors are elevated in POAG via a similar epigenetic mechanism as TGFβ2." (PMID 27403998, 2016). "While we chose to use Dex to model the TM dysfunctions that lead to decreased aqueous humor drainage, increased IOP and glaucoma, elevated levels of the cytokine TGFβ2 in aqueous humor have also been linked to pathological changes in the TM and glaucoma." (PMID 27783649, 2016). "Our results suggest that histone acetylation has an important role in increased expression of the glaucoma-associated factor TGFβ2." (PMID 27403998, 2016). "Interestingly, changes in the expression of TGFβ2 in the trabecular meshwork as well as optic nerve head have also been associated with glaucoma." (PMID 39543684, 2024). "Also, since family history is another important risk factor of glaucoma, it would be interesting to find out if genetics plays a role in elevated TGFβ2 or TGFβ signaling." (PMID 34499703, 2021). "Additionally, we used in vitro and ex vivo models to demonstrate that TDP-A induced histone hyperacetylation in the TM, which increased the expression of glaucoma-associated factor TGFβ2 as well as elevated IOP." (PMID 27403998, 2016).
glaucoma (continued). "To determine whether histone hyperacetylation can affect the expression of the glaucoma-associated factor TGFβ2 in the TM, we treated primary NTM cells with 10 nM TDP-A or 1% DMSO as a vehicle control for 4 days." (PMID 27403998, 2016). "Taken together, our results showed that histone hyperacetylation may have an important role in the increased expression of glaucoma-associated factor TGFβ2." (PMID 27403998, 2016). "In contrast, we found that HDAC inhibitors may adversely upregulate the expression of glaucoma-associated factors such as TGFβ2, leading to elevated IOP." (PMID 27403998, 2016). "Although TGFβ2 and other glaucoma-associated factors have been identified and studied for years, the regulatory mechanism that causes high ocular TGFβ2 expression is unknown." (PMID 27403998, 2016). "The glaucoma-associated factor TGFβ2 is increased in aqueous humor and TM of POAG patients." (PMID 27403998, 2016). "Evidence suggests that low estrogen (E2) and high TGFβ2 levels are risk factors for elevated IOP and primary open-angle glaucoma." (PMID 41800843, 2026). "The risk for developing primary open-angle glaucoma (POAG) correlates with the magnitude of ocular hypertension (OHT) and the concentration of transforming growth factor-β2 (TGFβ2) in the aqueous humor." (PMID 39574569, 2025). "Patients with this form of glaucoma have been found to have elevated levels of transforming growth factor beta-2 (TGF-β2) in the aqueous humor." (PMID 40243897, 2025). "Our central finding is that the glaucoma-inducing cytokine TGFβ2 amplifies TRPV4 expression and activity, which in turn drives tonic increases in TRPV4 activation and TM contractility that are required to maintain elevated IOP." (PMID 39574569, 2025). "Significant amounts of TGFβ2 were found at the optic nerve head of glaucoma patients, and TGFβ2 can directly increase ECM production by cells isolated from the optic nerve head." (PMID 38717426, 2024). "Another option to induce glaucoma in mice is the usage of TGFB2, a profibrotic cytokine elevated in the aqueous humor of patients with POAG29,30." (PMID 39313534, 2024). "It is of considerable interest that TGFβ2 was identified as a factor that contributes to barrier dysfunction, as previous studies have documented the elevation of TGFβ2 in the eyes of patients with glaucoma." (PMID 39543684, 2024). "Taken together, TGFβ2 signaling has the ability to interact with and influence both the front and back of the eye in glaucoma disease progression." (PMID 37686046, 2023). "TGFβ is a key driver of ECM production and fibrosis in the TM and TGFβ2 has been shown to be increased in the aqueous humor of patients with glaucoma." (PMID 38223904, 2023). "The AH from glaucoma patients contains increased TGFβ2 levels, which are thought to contribute to the fibrotic phenotype and extracellular matrix deposition reported in the glaucomatous outflow pathway." (PMID 37620383, 2023). "The concentration of transforming growth factor beta 2 (TGF-β2) is increased in aqueous humor of primary open angle glaucoma (POAG) patients." (PMID 37316554, 2023). "The concentration of transforming growth factor beta 2 (TGF-β2) is increased in the aqueous humor of primary open angle glaucoma patients." (PMID 37316554, 2023). "Studies of transforming growth factor-beta 2 (TGFβ2) have revealed its effects on increasing cross-linking enzymes and ECM deposition and a potential glaucoma-TGFβ2 relationship." (PMID 35652098, 2022). "TGFβ2 is highly elevated in the aqueous humor of glaucoma patients and plays a vital role in the development of POAG." (PMID 35912101, 2022). "Primary open-angle glaucoma progression is associated with increased human trabecular meshwork (HTM) stiffness and elevated transforming growth factor beta 2 (TGFβ2) levels in the aqueous humor." (PMID 35300422, 2022). "It is well established that TGFβ2 signaling increases in glaucoma and is known to affect the ONH during disease progression." (PMID 36911656, 2022).
glaucoma (continued). "Primary open angle glaucoma (POAG) features an optic neuropathy, elevated aqueous humor (AH) TGFβ2, and major risk factors of central corneal thickness (CCT), increasing age and intraocular pressure (IOP)." (PMID 35739142, 2022). "TGFβ2 levels are elevated in the aqueous humor of glaucoma patients compared to age-matched normal eyes." (PMID 35300422, 2022). "During glaucoma, the aqueous humor contains elevated levels of TGFβ2, exceeding levels for homeostatic signaling." (PMID 34776983, 2021). "TGFβ2 is a pro-fibrotic growth factor involved in the glaucoma pathogenesis, and it is found to be elevated in the AH of glaucoma patients." (PMID 34831087, 2021). "Transforming growth factor-beta 2 (TGF-β2) is highly concentrated in the aqueous humor of primary open-angle glaucoma patients." (PMID 34389355, 2021). "Elevated levels of bioactive TGFβ2 are present in the AH from glaucoma patients and are believed to contribute to the increased ECM deposition and fibrosis in the glaucomatous TM4–6." (PMID 31695131, 2019). "TGFβ-2 is an anti-proliferative and anti-inflammatory cytokine, which has been discussed in the context of various disorders, including glaucoma." (PMID 29675026, 2018). "Lerdelimumab (targeting TGFβ2) did show promise in glaucoma surgery by reducing scarring during subconjunctival wound healing in a randomized study in rabbits." (PMID 29615587, 2016). "We have provided evidence supporting the role of epigenetic regulation of TGFβ2 as a glaucoma mediator that elevates IOP." (PMID 27403998, 2016). "The TGFβ2 antibody CAT-152 has been shown to reduce collagen deposition in the subconjunctival following subconjunctival glaucoma surgery and improved surgical outcome in rabbits." (PMID 24800062, 2014). "A recombinant monoclonal neutralizing antibody (mAb) to human TGFβ2 was shown to significantly improve the outcome of glaucoma filtration surgery in a rabbit model of conjunctival scarring." (PMID 24800062, 2014). "TGFβ2 levels are elevated in the aqueous humor of patients with primary open-angle glaucoma." (PMID 38717426, 2024). "In addition, numerous studies have identified elevated aqueous humor levels of TGFβ2 in glaucoma patients." (PMID 36911656, 2022). "TGFβ1 has also been found to be elevated in the AH, along with TGFβ2, of patients with clinically active glaucoma and has also been found to be involved with the activation of thrombospondin-I via induction through dexamethasone (DEX) in TM cells, resulting in stress conditions." (PMID 35252223, 2021). "The dysregulation of TGFβ2 signaling and aberrant miR-29 expression may contribute to LC tissue remodeling in glaucoma." (PMID 34201109, 2021). "Clinically, glaucoma induced by TGFβ2, CTGF and glucocorticoids (GC) is very similar." (PMID 34440692, 2021). "Our findings suggest that downregulation of miR-29c-3p in glaucoma and TGFβ2 treated LC cells disrupts the ONH ECM and may affect the laminar tissue homeostasis, leading to pathogenic damage to the glaucomatous ONH." (PMID 34201109, 2021). "In this paper we show that activation of αvβ3 integrin signaling in trabecular meshwork cells causes a differential expression of multiple genes that contribute to TGFβ2 signaling and fibrotic-like changes that could lead to the development of glaucoma." (PMID 34440692, 2021). "Our research group and others have shown that expression of TGFβ2 is higher in glaucomatous LC tissue compared to normal age-matched controls and is implicated in altered gene expression and increased ECM deposition in glaucoma." (PMID 34201109, 2021). "TGFβ2 was reported to be higher in aqueous humour of glaucoma patients." (PMID 32267082, 2020). "Among other factors, TGFβ2 and SFRP1 have been implicated to be involved in glaucoma pathogenesis." (PMID 31382918, 2019). "Numerous studies have confirmed elevated levels of TGFβ2 in the AH of patients with glaucoma." (PMID 31695131, 2019).